HNRNPH3 (heterogeneous nuclear ribonucleoprotein H3)
Description:
Involved in the splicing process and participates in early heat shock-induced splicing arrest. Due to their great structural variations the different isoforms may possess different functions in the splicing reaction.
Synonyms: HNRPH3; 2H9
Tractability: PROTAC: UniProt records ubiquitination sites on it; ubiquitination databases record sites on it; its protein half-life has been measured.
Gene: Protein-coding gene on chromosome 10 (68,331,174 to 68,344,002, forward strand). Ensembl gene ENSG00000096746.
Subcellular location: Nucleus
Subcellular location (Human Protein Atlas): Nucleoplasm
Gene Ontology:
Molecular function: protein binding; RNA binding; nucleic acid binding
Biological process: epithelial cell differentiation; mRNA splicing, via spliceosome; regulation of RNA splicing; RNA processing; RNA splicing
Cellular component: nucleoplasm; nucleus; ribonucleoprotein complex; spliceosomal complex
Genetic constraint (gnomAD): Loss-of-function variants: 2 observed, 20.69 expected, observed/expected ratio (o/e) 0.0967, 90% interval 0.039 to 0.3. The upper end of that interval is the gene's LOEUF score, 0.3, which puts it in group 1 of 6, group 1 being the genes least tolerant of losing a copy. Missense variants: 173 observed, 269.58 expected, observed/expected ratio (o/e) 0.64, 90% interval 0.57 to 0.73. Synonymous variants: 69 observed, 85.65 expected, observed/expected ratio (o/e) 0.81, 90% interval 0.66 to 0.98.
Homologues: Orthologues: chimpanzee HNRNPH3 (100% identical), dog HNRNPH3 (100% identical), guinea pig HNRNPH3 (100% identical), macaque HNRNPH3 (100% identical), pig HNRNPH3 (100% identical), rabbit HNRNPH3 (100% identical), mouse Hnrnph3 (99% identical), rat Hnrnph3 (99% identical), tropical clawed frog hnrnph3 (80% identical), Drosophila melanogaster glo (38% identical), Drosophila melanogaster fus (22% identical), Caenorhabditis elegans sym-2 (19% identical), and 3 more. Paralogues in human: HNRNPH1 (64% identical), HNRNPH2 (63% identical), HNRNPF (56% identical), GRSF1 (31% identical), ESRP1 (25% identical), ESRP2 (25% identical), RBM12 (21% identical), RBM12B (20% identical).
Diseases named in the same sentence as HNRNPH3 in open-access papers:
HNRNPH3 is named in the same sentence as 9 diseases in open-access papers, as found by Europe PMC text mining. Sharing a sentence is not in itself a finding about the gene and the disease. The quoted sentences say what the papers report.
Hearing impairment (1 paper, 2021). A decreased magnitude of the sensory perception of sound. "Hearing impairment is observed primarily among probands with HNRNPH3 variation (66.7%, n = 2/3), although with only three probands its’ unclear if this is characteristic of a majority of HNRNPH3 variants." (PMID 33874999, 2021).
late-onset Alzheimers disease (1 paper, 2014). This is the most common form of the disease, which happens to people age 65 and older. "Other genes mapping in the deleted region, including DNAJC12 (MIM 606060), HERC4 (MIM 609248), PBLD (MIM 612189), HNRNPH3 (MIM 602324), RUFY2 (MIM 610328), STOX1 (MIM 609397), and CTNNA3 (MIM 607667), have been linked to late-onset Alzheimer’s disease (AD6; MIM 605526)." (PMID 24297458, 2014).
lung carcinoma (1 paper, 2025). "Similarly, we identified several splicing proteins, such as SNRPD2, SNRPG, SNRPD3, HNRNPM, HNRNPH3, and SRSF10, in human breast and lung cancer TuNEPs but not in NETs." (PMID 40751052, 2025).
prostate carcinoma (1 paper, 2021). A carcinoma that arises from epithelial cells of the prostate gland. "In addition, the expression levels of three proteins—TUFM, and HNRNPH3 from the DHT-specific proteome, and CCT2 from the FSK-specific proteome—were related to the progression-free interval in prostate cancer patients." (PMID 34680521, 2021).
salivary duct carcinoma (1 paper, 2021). An aggressive, high grade adenocarcinoma that arises from the salivary glands. "A study has found a novel HNRNPH3-ALK rearrangement in salivary duct carcinoma." (PMID 34484222, 2021).
cancer (3 papers, 2020 to 2023). A tumor composed of atypical neoplastic, often pleomorphic cells that invade other tissues. "Several RBPs exhibited widespread activities in various cell types and cancer types, such as HNRNPH3, HNRNPH1 and TIAL1." (PMID 36681772, 2023).
tumor (1 paper, 2019). "SFs HNRNPH3 and HNRNPL were overexpressed in tumor samples and were signifcantly associated with the OS of HCC patients." (PMID 31844595, 2019). "Compared to adjacent normal sample, the expression of HNRNPL and HNRNPH3 were higher in tumor sample." (PMID 31844595, 2019). "The top two counterpart SFs were HNRNPL and HNRNPH3, and the expression of HNRNPL and HNRNPH3 in tumor sample were significantly higher than adjacent normal sample." (PMID 31844595, 2019).
HNRNPH3 also shares sentences with these, for which no sentence is quoted: infection (1 paper); renal cell carcinoma (1).